LOXL2 (lysyl oxidase like 2)
Diseases named in the same sentence as LOXL2 in open-access papers (continued):
Sharing a sentence is not in itself a finding about the gene and the disease.
cancer (continued). "Recent studies using loss‐ or gain‐of‐functions approaches also indicate that LOXL2 regulates actin cytoskeletal reorganization in several cancers." (PMID 28556501, 2017). "Dysregulation of LOXL2 is strongly associated with fibrotic disorders, cardiovascular diseases, and cancers." (PMID 29089463, 2017). "LOXL2 encodes an extracellular copper-dependent amine oxidase, and it is over-expressed in various types of primary cancer tissues and cells." (PMID 27008697, 2016). "Several studies have reported that LOXL2 is associated with poor prognosis in cancer patients, and that overexpression of LOXL2 promotes invasion activity among cancer cells." (PMID 27285767, 2016). "Furthermore, LOXL2 mediates the crosstalk between cancer cells and cancer-associated fibroblasts, facilitating cancer metastasis." (PMID 40148559, 2025). "LOXL2 is abnormally overexpressed in patients with numerous cancers, could promote the proliferation, migration, invasion, and metastasis of cancer cells, and is associated with poor prognosis." (PMID 40148559, 2025). "LOXL2 loss has been linked to reduced migration in multiple cancer types." (PMID 41226485, 2025). "In addition, cancer-associated fibroblast-derived LOXL2 is an essential mediator of intercellular communication within the prostate TME and is a potential therapeutic target." (PMID 39149513, 2024). "In cancer, various external factors and the dysregulation of many intracellular signaling pathways may displace and cause an abnormal expression of LOXL2." (PMID 39329988, 2024). "However, a report revealed that LOXL2 overexpression is more common than mutation, follow-up studies are required for specific cancer types." (PMID 38922489, 2024). "Furthermore, LOXL2 has also recently been associated with cancer stem cells and plays a regulatory role in a MAPK signal-dependent manner." (PMID 37737908, 2023). "However, inhibition of LOXL2, which causes decreased matrix context and stiffness, promotes cancer progression in PDAC, suggests the organ specificity of ECM stiffness in oncogenesis." (PMID 36906534, 2023). "Among LOX family, the profound association between LOXL2 and cancer progression has been reported." (PMID 36906534, 2023). "Furthermore, among the identified dysregulated genes, LOXL2 has well-established associations with cancer invasiveness, metastasis and poor prognosis, which has been also linked to EMT promotion." (PMID 36465388, 2022). "In our study, we found that high-LOXL2 cluster showed younger mean diagnostic age, while high-LOXL2 cluster showed poor cancer survival, which meant the poor prognosis in high-LOXL2 cluster was not completely on account of age at initial pathological diagnosis." (PMID 32211324, 2020). "The underlying mechanisms of the effect of LOXL2 on invasiveness of cancer are not well understood." (PMID 31086173, 2019). "High abnormal expression of LOX and LOXL2 was also observed in the epithelium of dysplastic tissue, suggesting a possible role in dysplasia that may ultimately be a factor in cancer development in combination with mutations and environmental influences." (PMID 31086173, 2019). "Among 13 genes at the LOH locus, LOXL2 expression was shown to be increased in patients with liver metastasis, compared with that in the normal tissues or matched primary cancer by locus mutation, which supports our conclusion that LOXL2 induces EMT/metastasis." (PMID 29113306, 2017).
cancer (continued). "In addition, we observed high LOXL2 that are markers of a stiff cancer-associated matrix that affects cell adhesion, cell migration, cancer stem cell characteristics and EMT." (PMID 29176937, 2017). "Lysyl oxidase-like 2 (LOXL2) is associated with invasiveness and metastasis in cancer." (PMID 27285767, 2016). "Moreover, we performed in vitro studies that showed an association between an aggressive cancer prognosis and LOXL2 expression." (PMID 27285767, 2016). "Decreased LOXL2, encoding lysyl oxidase-like 2 delta E13 (essential to connective tissue biogenesis, which catalyzes the first step in forming crosslinks in collagen and elastin), could contribute to the inhibition of cancer invasiveness." (PMID 37834191, 2023). "Furthermore, collagens XIII and XVII are both associated with cancer, and their interactions with LOXL2 could also occur in this context." (PMID 33383846, 2020). "Thus, we hypothesized that high LOXL2 expression showing poor cancer survival may be associated with the EMT phenotype." (PMID 32211324, 2020). "At the same time, we experimentally tested the effect of potential LOXL2 inhibitors on cancer cells." (PMID 40148559, 2025). "Numerous investigations have demonstrated that LOXL2 expression is markedly changed in several cancer types, including lung cancer, aggressive osteosarcoma, pancreatic ductal adenocarcinoma, prostate, colorectal, and breast cancer." (PMID 39877633, 2025). "The role of LOXL2 in cancer has been widely demonstrated, but current therapies targeting LOXL2 are not yet fully developed." (PMID 40148559, 2025). "The five EMRGs in our model—LOXL2, RUNX2, NCKAP1L, WFS1, and SPTBN1—have been implicated in diverse cancer-related processes." (PMID 41164190, 2025). "LOXL2 has been shown to have an important role in certain fibrotic diseases and cancers, and selective inhibition of LOXL2 has received extensive research attention for its potential therapeutic advantages in treating these diseases." (PMID 40148559, 2025). "Our thorough investigation brought to light the possible therapeutic importance of LOX family‐specifically, LOX and LOXL2 in the advancement of cancer therapy strategies." (PMID 40179101, 2025). "Overexpression of LOXL2 has been correlated with poor prognosis in cancers such as gastric, breast, and squamous cell carcinomas." (PMID 40332376, 2025). "AB0023, an inhibitory antibody targeting LOXL2, effectively reduced disease markers in both cancer and fibrosis models." (PMID 40661776, 2025). "In recent years, LOXL2 has been reported to act as a multifunction enzyme involved in mediating numerous cellular processes in cancers." (PMID 41281746, 2025). "Barry-Hamilton discovered that LOXL2 drives the pathologic microenvironment of cancer and fibrotic diseases in lung and liver, with elevated levels in diseased stroma." (PMID 40661776, 2025). "This study aimed to comprehensively examine the landscape of LOXL2 in pan-cancer, encompassing its expression level, prognostic value, genetic alteration, and immune infiltration." (PMID 38922489, 2024). "LOX/LOXL inhibitors, specifically LOXL2 inhibitors, are used in cancer and fibrosis to prevent collagen crosslinking." (PMID 38659022, 2024). "This comprehensive analysis offers valuable insights on the functions of LOXL2 in different types of cancer and its role in regulating the senescence of cancer cells." (PMID 38922489, 2024). "Another study demonstrated that the reduction of METTL1/WDR4 hinders the translational efficacy of the oncogene lysyl oxidase-like 2 (LOXL2), which is a cancer-causing enzyme that promotes the cross-linking of elastin and collagen in the extracellular matrix." (PMID 39019857, 2024). "The accumulation of LOXL2 in the endoplasmic reticulum (EPR) of cancer cells, which occurs in tumors of higher grade, initiates the ERR-stress response due to the interaction of LOXL2 and heat shock 70 kDa protein 5 (HSPA5)." (PMID 39329988, 2024).
cancer (continued). "It makes LOXL2 detectable in blood samples of patients with lung SCC, pointing to LOXL2 as a potential biomarker of this form of cancer." (PMID 39329988, 2024). "In turn, the interaction of LOXL2 with myristoylated alanine-rich C kinase substrate-like 1 (MARCKSL1) improves the survival of cancer cells by inhibiting the MARCKSL1-induced apoptosis." (PMID 39329988, 2024). "Further analysis revealed the participation of LOXL2 in multiple pathways related to cancer extracellular matrix remodeling and cellular senescence." (PMID 38922489, 2024). "The findings across multiple types of cancer are in line with previous results obtained from studies focused on a singular type of cancer, and indicating LOXL2 as a possible predictive biomarker for multiple cancers." (PMID 38922489, 2024). "In contrast, the fibroblasts expressed relatively higher levels of LOX and LOXL2, suggesting that the fibroblasts exhibit a different hypoxia expression profile than the cancer cells." (PMID 39011470, 2024). "The top 100 genes with the most comparable expression patterns to LOXL2 in pan-cancer were extracted from GEPIA2." (PMID 38922489, 2024). "The main genetic alteration type of LOXL2 in pan-cancer is “Deep Deletion” and UCEC, SKCM, and COAD had the highest mutated frequencies of 5.9%, 4.6%, and 3.5%, respectively." (PMID 38922489, 2024). "In the extracellular milieu, the presence of LOXL2 was found to enhance stromal stiffness and facilitate the promotion of adjacent fibroblasts, thereby establishing a supportive niche within the cancer microenvironment." (PMID 38922489, 2024). "The main genetic alteration type of LOXL2 in pan-cancer is “Deep Deletion” and the top 3 cancer types with high alteration frequencies were UCEC, SKCM, and PRAD." (PMID 38922489, 2024). "Notwithstanding the significance of regulation in the context of cancer, it appears that this is the inaugural pan-cancer analysis of LOXL2 conducted thus far." (PMID 38922489, 2024). "We conducted research to explore the correlations between the expression of LOXL2 and the immune environment in various types of cancer." (PMID 38922489, 2024). "In this review, we aim to provide a comprehensive overview of two decades of research on the role of LOXL2 in cancer." (PMID 37762708, 2023). "This novel and specific ELISA assay appears to be another approach for detecting elevated LOXL2 levels in fibrosis or cancer." (PMID 37762708, 2023). "All these findings provide insights into the intricate regulatory network governing LOXL2 expression and activity in various cancer types." (PMID 37762708, 2023). "Here, we show that LOXL2 expression can predict the outcome of BETi treatment in cancer cells, suggesting a functional interaction between LOXL2 and BRD4." (PMID 37937685, 2023). "In summary, LOXL2 involvement in various types of cancer is multifaceted, as it targets different cellular compartments and participates in numerous signalling pathways." (PMID 37762708, 2023). "Subsequent studies showed that LOXL2 expression was increased in the context of several fibrotic conditions including those in the liver, heart, cancer, eye, and lung." (PMID 38873180, 2023). "Intracellular LOXL2 exerts its pro-tumorigenic role by modifying different cytoplasmic targets and regulating various signalling pathways in different cancer systems." (PMID 37762708, 2023). "LOXL2 transcription is also regulated in different cancer scenarios by a series of factors whose mechanisms are still not fully characterised." (PMID 37762708, 2023). "By analyzing the Cancer Cell Line Encyclopedia (CCLE)‐associated chemotherapeutics sensitivity, we observed that high levels of LOXL2 expression make cells significantly more sensitive to Vinca alkaloid compounds." (PMID 37937685, 2023). "Lysyl oxidase-like protein 2 (LOXL2) is known for its contribution towards cancer advancement and metastasis in various cancer entities including PDAC." (PMID 37444617, 2023).
cancer (continued). "For example, exploration of epigenetic mechanisms that regulate fibroblast activity in cancer point to the role of miR-29a and its direct effect on both LOXL2 and serpin peptidase inhibitor clade H, member 1 (SERPINH1)." (PMID 38873180, 2023). "The top 5 identified genes affecting survival negatively (p < 0.05) in at least 4/9 cancer types were LOXL2, ITGA3, ACTB, EFNB2 and ITGB1." (PMID 37206618, 2023). "As evidence for the high expression of LOXL2 in several types of cancer has increased, the possibility of considering LOXL2 as a potential prognostic marker has also grown." (PMID 37762708, 2023). "Understanding the mechanisms controlling LOXL2 expression and function can potentially lead to the development of targeted therapies for cancer treatment in the near future." (PMID 37762708, 2023). "To investigate the connection between hypoxia and COZP1, we analyzed the correlation of COPZ1 and HIF1A as well as the LOXL2 in 33 cancer types." (PMID 37107648, 2023). "In normal mammary epithelial cells, LOXL2 overexpression induces oncogenic transformation and cancer progression by activating the Erb-B2 receptor tyrosine kinase 2 (ERBB2) through the production of reactive oxygen species (ROS)." (PMID 37762708, 2023). "In MCF-7 mammosphere 3D cultures with basement membrane extract (BME), LOXL2 induced-expression was shown to promote the reawakening of these spheres by acquiring a cancer stem cell-like and an epithelial to mesenchymal transition (EMT) phenotype." (PMID 37442876, 2023). "Specifically focusing on LOXL2-induced cancer progression, various attempts have recently been made to develop inhibitors." (PMID 37737908, 2023). "Reciprocally, Loxl2 overexpression promotes cancer growth with lowered OS and poor prognostic outcomes, which is ascribed from enhanced EMT and the increased acquisition of cancer stem cells." (PMID 37444617, 2023). "In conclusion, LOXL2 is a promising target for cancer therapy and the development of anti-LOXL2 drugs appears feasible." (PMID 37762708, 2023). "Some syngeneic cancer cell models have also been reported in which the expression of Loxl2 has been genetically manipulated and the resulting cell lines orthotopically injected into immune-competent syngeneic mouse lines, providing valuable preclinical models." (PMID 37762708, 2023). "GEPIA platform was used to analyze the prognostic value of LOXL2 in pan-cancers, and OS is selected to be the outcome indicator." (PMID 36254230, 2022). "Next, to further confirm this result, the GEPIA database was also used to evaluate the LOXL2 expression levels in these cancers." (PMID 36254230, 2022). "As observed earlier with Loxl2, Kif5b staining in cancer cells and immediate stroma showed a strong positivity while in the normal pancreas, the acini were strongly positive but adjacent stroma was weakly positive for Kif5b expression." (PMID 36002889, 2022). "Critically, Loxl2 maintains transcriptional regulation of genes that play a role in age-related diseases including cancers and cardiovascular disease genes." (PMID 34734976, 2022). "In this present study, the expression of LOXL2 in various cancers was analyzed using different databases (TCGA database and GEPIA database), and it was concluded that LOXL2 was significantly differentially expressed in HCC." (PMID 36254230, 2022). "Enzyme containing copper ions, such as lysyl oxidase like two proteins (LOXL2), can produce collagen scaffold structures and help cancer cells migrate." (PMID 36699089, 2022). "The qRT-PCR results from 10 paired LUAD samples showed that the expression of SOD3 and SLC31A2 in cancer tissues was significantly lower than that in normal lung tissues, whereas LOXL2 has highly expression in LUAD tissues (P < 0.05)." (PMID 36524120, 2022). "This is consistent with previous reports that LOXL2 has key pathologic roles in cancer and fibrosis." (PMID 35188460, 2022).
cancer (continued). "Overexpression of LOXL2 or L2Δ13 conversely inhibited aldolase A-K13 acetylation in both cancer cells and mice." (PMID 36209516, 2022). "Lastly, LOXL2 secretion has been shown to induce collagen crosslinking and adaptation via acidosis, promoting survival and growth of nascent cancers." (PMID 36010848, 2022). "In this study, the expression level of the LOXL2 and its relationship with prognosis were first analyzed in various common cancers." (PMID 36254230, 2022). "Overexpression of LOXL2 is associated with a more aggressive invasive phenotype, which is associated with an epithelial-mesenchymal-transition (EMT) phenotype and drives cancer metastasis." (PMID 35205728, 2022). "ATP formation was completely rescued and lactate production increased to background levels following ectopic expression of LOXL2 or L2Δ13, suggesting that LOXL2 and L2Δ13 specifically promote glycolysis in cancer cells." (PMID 36209516, 2022). "The allosteric function of the disulfide bond in LOXL2 corresponds to the ability of metastasis and invasion of cancer cells, and the catalytic function corresponds to the enzyme activity." (PMID 34970534, 2021). "As an example, we also simulated the migration of individual mesenchymal cancer cells through such a heterogeneous, LOXL2-modified ECM." (PMID 33807227, 2021). "Another LOXL inhibitor to show early promise in cancer treatment was the anti-LOXL2 monoclonal mouse antibody AB0023, which was effective in reducing intratumoral collagen density in vivo in a murine model of pancreatic cancer." (PMID 33513979, 2021). "There was also a weak to moderate positive, significant correlation between OSMR and LOXL2 expression in the other cancers investigated." (PMID 34011405, 2021). "LOXL2 overexpression seems to enhance the ability of cancer cells to invade tissue layers and promote metastasis." (PMID 33804181, 2021). "Considering the therapeutic potential of blocking LOXL2 in cancer treatment, several inhibitors of this protein have been developed." (PMID 33669630, 2021). "To assess the correlation between OSMR and LOXL2, we used RNA-Seq data from The Cancer Genome Atlas (TCGA) to assay transcriptional expression of biopsied patient samples in several cancer subtypes." (PMID 34011405, 2021). "RTKN2, NFIX, PTX3, BMP2 and LOXL2 of the ceRNA network play an important role in cancer progression." (PMID 34394080, 2021). "A simplified biophysical setup is simulated, where a geometrically localized cluster of cancer cells secretes LOXL2 that is then subject to diffusion and degradation." (PMID 33807227, 2021). "LOX/LOXL2 levels are often increased in cancer, resulting in increased collagen deposition and stiffening of the ECM, thereby facilitating metastatic cell engraftment." (PMID 34426581, 2021). "To assess the correlation between OSM signaling and LOXL2 expression in cancer patients, we analyzed the expression of LOXL2 mRNA in patients and compared it to OSMR mRNA expression." (PMID 34011405, 2021). "We found that the average expression of LOXL2 was elevated in primary cancer compared with normal cervix tissue." (PMID 32211324, 2020). "We identified 31 new interactions and 14 new partners of LOXL2 and its N-terminal domains, including the α5β1 integrin, involved in both angiogenesis and cancer." (PMID 33383846, 2020). "Further, research has shown that a short isoform of LOXL2 missing exon 13 can regulate cancer cell migration and invasion through a dissimilar mechanism compared to its canonical form." (PMID 32064050, 2020). "Upregulated LOXL2 was also significantly correlated with higher pathological stages, cancer cell survival, invasion, and metastasis in KIRC." (PMID 32970930, 2020). "Of note, LOXL2 expression is probably involved in more types of cancer, which is consistent with the previous report." (PMID 32424143, 2020).